DAPK1 (death associated protein kinase 1)
Diseases named in the same sentence as DAPK1 in open-access papers (continued):
Sharing a sentence is not in itself a finding about the gene and the disease.
breast carcinoma (continued). "Previous studies have found that the DAPK1 gene is abnormally methylated in a variety of tumors, including brain metastases, squamous cell carcinoma, gliomas, high-grade cervical lesions, breast cancer, myelodysplastic syndrome, gastric cancer and non-small cell lung cancer (NSCLC) 33-40." (PMID 37576398, 2023). "DAPK-1 mRNA and protein expression were also shown to be below the limit of detection in some neoplastic-derived B-cell lines, bladder carcinoma, renal cell carcinoma and breast carcinoma cell lines when compared to the positive control cell lines." (PMID 37372454, 2023). "Except for DAPK1, all other component genes of Overlap36sub are associated with T cell dysfunction in multiple cancer types among neuroblastoma, acute myeloid leukemia (AML), breast cancer, endometrial carcinoma, and melanoma." (PMID 36588164, 2023). "Furthermore, the most potent DAPK1 inhibitor (4q) exhibited remarkable activity against leukemia (K-562) and breast cancer (MDA-MB-468) with % GI of 72% and 75%, respectively." (PMID 36145271, 2022). "Promoter methylation of DAPK1, for example, is a characteristic feature of breast cancer." (PMID 35421941, 2022). "The augmented serum levels of DAPK1 may be an indication of the perturbations within cells of breast cancer patients at the molecular level." (PMID 32566040, 2020). "DAPK1 levels were higher in sera and breast tissues of breast cancer patients than controls." (PMID 32566040, 2020). "DAPK1 may have potential application as a blood biomarker for breast cancer as well as the prospect for developing new therapeutic strategies." (PMID 32566040, 2020). "It is therefore worth investigating DAPK1 and its functional relevance in breast cancers." (PMID 32566040, 2020). "Similarly with DAPK1, it has been observed to be significantly elevated in certain types of breast cancers, which are typically more aggressive with poor prognosis." (PMID 28616237, 2017). "Since elevated vimentin and DAPK1 serum levels correlate postively with aggressiveness of breast cancer and are higher in “young” people, this might support the reasons why breast cancer in Ghanaian women tends to be more aggressive." (PMID 28616237, 2017). "Vimentin and DAPK1 should be explored further as potential breast cancer biomarkers in Africans." (PMID 28616237, 2017). "Putting these data together, DAPK1 expression may give a selective advantage to the growth rate of breast cancer cells." (PMID 28616237, 2017). "Our results provide evidence that ITIH5 triggers a reprogramming of breast cancer cells with known stem CSC properties towards an epithelial-like phenotype through global epigenetic changes effecting known tumor suppressor genes like DAPK1." (PMID 28231808, 2017). "Serum concentration of Vimentin and DAPK1 are elevated in Ghanaian breast cancer patients." (PMID 28616237, 2017). "This mutation is abundant in breast cancers which are negative for oestrogen hormone receptor but DAPK1 and Vimentin expression profiles in breast cancer in African women are not known." (PMID 28616237, 2017). "The elevated serum levels of DAPK1 may suggest the cellular perturbations occurring within cells of breast cancer patients." (PMID 28616237, 2017). "However, DAPK1 levels were relatively substantial in the sera of both breast cancer patients and the controls even though that of the controls was significantly lower than that of the breast cancer patients." (PMID 32566040, 2020). "Interestingly, in aggressive mammary cancer cells, ITIH5 triggered an epigenetic reprogramming which was associated with a demethylation of various promoter regions, including that of DAPK1, a tumor suppressor gene and putative blood-based biomarker in several tumor entities." (PMID 32046186, 2020).
breast carcinoma (continued). "As DAPK1 (death-associated protein kinase (DAP Kinase)) is a well-known tumor suppressor, we aimed to demonstrate whether its re-expression may explain some of the ITIH5-associated suppressive attributes in basal-type breast cancer cells." (PMID 28231808, 2017). "For example, ITIH5 suppressed breast cancer metastasis and induced cell death by regulating TGF-β superfamily signalling switches, and elevated the expression of the tumour-suppressor gene DAPK1 by modulating epigenetic reprogramming." (PMID 33935281, 2021). "Altogether, these data strongly suggest that DNA hypermethylation is involved in the transcriptional silencing of DAPK1 and NTN1 in human breast cancer cells." (PMID 27378792, 2016). "The relationship between DAPK1/NTN1 downregulation and DNA hypermethylation was also observed in a larger number of breast cancer samples (n = 807) available on TCGA data portal." (PMID 27378792, 2016). "MS-HRM analysis was carried out to determine the methylation status of CCND2, DAPK1, GSTP1, HIN-1, MGMT and RASSF1A promoters in tumor tissues and histologically normal-appearing tumor-adjacent and tumor-distant tissues of 17 breast cancer patients." (PMID 26370119, 2015). "CCND2, DAPK1, GSTP1, HIN-1, MGMT and RASSF1A were selected because they have previously been reported to be frequently methylated in primary breast cancers." (PMID 26370119, 2015). "Our previous studies with breast cancer specimens demonstrated that the methylation of DAPK1 gene did not correlate well with DAPK1 protein level." (PMID 40918124, 2025). "Our previous study found that DNA methylation status of DAPK1 did not correlate well with its mRNA or protein expression in breast cancer, which indicated that DAPK1 expression is not only regulated by methylation." (PMID 34422899, 2021). "We report that DAPK1 expression levels in both sera and breast tissue samples are higher in breast cancer patients than in their nonbreast cancer counterparts." (PMID 32566040, 2020). "DAPK1 is highly expressed in sera and breast tissues of breast cancer patients than nonbreast cancer participants." (PMID 32566040, 2020). "We have previously reported that DAPK1 was elevated in archived serum samples of breast cancer patients compared to nonbreast cancer individuals and thus the protein was associated with aggressive breast tumour phenotypes in Ghanaians." (PMID 32566040, 2020). "In our study, serum levels of vimentin and DAPK1 have been shown to be elevated in Ghanaian breast cancer patients than in their non-cancer counterparts." (PMID 28616237, 2017). "In a previous study, we determined the promoter methylation status of six tumor suppressor genes (CCND2, DAPK1, GSTP1, HIN-1, MGMT and RASSF1A) in tumor, tumor-adjacent and tumor-distant tissues from breast cancer patients and normal breast tissues from healthy controls." (PMID 28403857, 2017).
cervical carcinoma (40 papers, 2006 to 2026). A carcinoma arising from either the exocervical squamous epithelium or the endocervical glandular epithelium. "DAPK-1 can be regarded as a tumour suppressor, since its hypermethylation and loss of its expression have been shown in many types of cancers, including cervical cancer." (PMID 37372454, 2023). "In the present study, we demonstrate for the first time that the kinase activity of the death-associated protein kinase 1 (DAPK1) is regulated in a cell cycle-specific manner in cervical cancer cells." (PMID 35154442, 2022). "This systematic meta-analysis revealed that DAPK1 promoter methylation was associated with an increased cervical cancer risk." (PMID 35154442, 2022). "DAPK1 has been shown to be associated with the severity of cervical cancer; DAPK1 upregulation suppresses tumor cell proliferation and improve apoptosis and autophagy." (PMID 32328088, 2020). "The Death-Associated Protein Kinase 1 (DAPK1) gene has been frequently investigated in cervical cancer (CC)." (PMID 26267895, 2015). "Considering that the quality and quantity of the reviewed articles were limited, larger and well-designed studies should be employed in the future for further confirmation of the association between DAPK1 promoter methylation and cervical cancer." (PMID 25268905, 2014). "During the past several decades, many studies have explored the association between DAPK1 promoter methylation and cervical cancer." (PMID 25268905, 2014). "When the heterogeneous study was omitted, the pooled OR value was increased from 15.32 to 21.80 (the fixed effects model), which suggested a stronger association between DAPK1 promoter methylation and cervical cancer." (PMID 25268905, 2014). "The ORs and 95% CIs were calculated to assess the association between DAPK1 promoter methylation and cervical cancer risk." (PMID 25268905, 2014). "A strong association was observed between DAPK1 promoter methylation and cervical cancer with a pooled OR of = 19.66 (95%CI = 8.72–44.31) based on the random effects model." (PMID 25268905, 2014). "DAPK-1 is considered a tumor suppressor due to its hypermethylation and loss of expression, which have been observed in various types of malignancies, including cervical cancer." (PMID 39081443, 2024). "Numerous malignancies have been linked with DAPK-1 hypermethylation and loss of its expression, and these include bladder, kidney, gastric, head and neck, thyroid, lung, ovarian and cervical cancers." (PMID 37372454, 2023). "At present, the treatment of recurrent cervical cancer remains largely ineffective, and efforts in cancer drug development are currently focused on critical serine/threonine kinases, such as death-associated protein kinase 1 (DAPK1) and polo-like kinase 1 (PLK1)." (PMID 35154442, 2022). "The results suggested a strong association between DAPK1 promoter methylation and cervical cancer." (PMID 25268905, 2014). "Subgroup meta-analysis of the association between DAPK1 promoter methylation and cervical cancer." (PMID 25268905, 2014). "Thus, we conducted a meta-analysis to assess the association between DAPK1 promoter methylation and cervical cancer." (PMID 25268905, 2014). "Because DAPK1 is an important tumor suppressor gene that has been studied extensively, we performed a meta-analysis to assess the association between DAPK1 promoter methylation and cervical cancer." (PMID 25268905, 2014). "The loss of DAPK1 expression, mainly by hypermethylation of its promoter region, enhances the metastatic potential of cancer cells and has been proven to occur in a variety of cancers, including cancer of the uterine cervix." (PMID 25268905, 2014). "In conclusion, a significant association between the methylation of DAPK1 promoter which correlates inversely with the expression level of DAPK1 and cervical cancer malignancy was demonstrated previously suggesting an important role of DAPK1 for the aggressiveness of cervical cancer." (PMID 35154442, 2022).
cervical carcinoma (continued). "the result of the pooled OR was 19.66 (95%CI = 8.72–44.31) with the random effects model, which showed that DAPK1 promoter methylation is associated with cervical cancer and therefore, that it might play an important role in the pathogenesis of cervical cancer." (PMID 25268905, 2014). "The hypermethylation of the CpG island in the DAPK1 promoter region was examined in a series of tumor tissue and cancer cells, such as cervical cancer, gliomas, and colorectal cancer." (PMID 35321516, 2022). "The present study demonstrated that, in cervical cancer cells, the enzymatic activity of DAPK1 was regulated in a cell cycle-specific manner." (PMID 35154442, 2022). "Specifically, we characterized aberrantly methylated host promoter genes (RARB, CADM1, DAPK1, and PAX1) and their possible association with: invasive cervical cancer, cervical cancer stage, HIV status, age, high-risk HPV genotypes." (PMID 33718129, 2021). "Cervical cancer and promoter methylation of RARB and DAPK1 genes were associated with increasing age (OR = 1.12; 95% CI: 1.01-1.26; P = 0.037 and OR = 1.05; 95% CI: 1.00-1.10; P = 0.040)." (PMID 33718129, 2021). "Several studies have demonstrated promoter methylation of DAPK1 in different types of cancer such as renal and cervical cancer, B cell lymphoma, myelodysplastic syndrome, acute myeloblastic leukemia, and chronic myeloid leukemia." (PMID 30409182, 2018). "Here, we performed a meta-analysis to assess the associations of DAPK1 promoter hypermethylation with low-grade intra-epithelial lesion (HSIL), high-grade intra-epithelial lesion (HSIL), cervical cancer (CC), and clinicopathological features of CC." (PMID 30065752, 2018). "The frequencies of DAPK1 promoter methylation ranged from 30.0% to 78.6% (median, 59.3%) in cervical cancer tissue and 0.0% to 46.7% (median, 7.8%) in normal cervical tissue." (PMID 25268905, 2014). "Therefore, the current study examined the role of DAPK1 in topotecan-induced cervical cancer cell death, and it was identified that RNA interference-based silencing of DAPK1 decreased the apoptotic effect of topotecan." (PMID 35154442, 2022). "Notably, the downregulation of DAPK1 by RNAi reduced the apoptotic response to topotecan in cervical cancer cell lines and in primary cervical cancer samples, indicating that DAPK contributes to cell death signaling under topotecan treatment." (PMID 35154442, 2022). "Our study suggests that DAPK1 could be a biomarker and a potential target for the response to topotecan during the therapy of patients with cervical cancer." (PMID 35154442, 2022). "SiHa cervical carcinoma cells were used as methylated DAPK1 promoter controls." (PMID 28251343, 2018). "Alterations in DNA methylation of specific genes in cervical cancers, such as DAPK1, RARB, WIF1, and SLIT2, may also occur early in cervical carcinogenesis and should be evaluated." (PMID 25826459, 2015). "Interestingly, we found that DAPK1 methylation was one of the best overall predictors of cervical cancer." (PMID 25826459, 2015). "This study also indicated that DAPK1 promoter methylation may be a biomarker during cervical carcinogenesis that might serve as an early indication of cervical cancer." (PMID 25268905, 2014). "In conclusion, a strong association was observed between DAPK1 promoter methylation and cervical cancer, and therefore, DAPK1 promoter methylation may be valuable as a biomarker." (PMID 25268905, 2014). "Prominent alterations in DNA methylation in cervical cancers, such as shown for DAPK1, SLIT2, WIF1 and RARB, may also be early molecular events in cervical carcinogenesis and using the pyrosequencing assays developed here should be further tested in CIN3 lesions." (PMID 25826459, 2015).
cervical carcinoma (continued). "Subsequently, the interaction between endogenous DAPK1 and PLK1 in cervical cancer cells was visualized using the PLA, which depends on recognition of target proteins by pairs of antibody-oligonucleotide conjugates." (PMID 35154442, 2022). "After sorting the data, we selected MEG3, TIMP3, DAPK1, and SOX1 as being the most hypermethylated genes specific for the incipient stages of cervical carcinoma, while MLH1 and MALAT1 were chosen as the most hypomethylated genes." (PMID 35682732, 2022). "In the current study, we aimed at exploring the cell cycle roles of DAPK1 and PLK1 in cervical cancer cells." (PMID 35154442, 2022). "Our data further confirm the possible role of promoter methylation of RARB, CADM1, DAPK1, and PAX1 in cervical cancer tumorigenesis." (PMID 33718129, 2021). "The expression of E-cadherin, DAPK1, RARβ, p16INK4a, MGMT, FHIT, RUNX3, CDH1, PTEN, and SOC51 was also reactivated through genistein-induced promoter hypomethylation in cervical cancer cells." (PMID 32878338, 2020). "The remaining genes (DAPK1, RARB, SLIT2 and WIF1) were evaluated for their ability to identify cervical cancer cases in relation to HPV infection and age." (PMID 25826459, 2015). "Herein, we identified an epigenetic biomarker panel (DAPK1, SLIT2, WIF1 and RARB) that distinguished cervical cancers from normal cytology samples." (PMID 25826459, 2015). "Pyrosequencing analysis confirmed earlier studies indicating that DAPK1, SLIT2, WIF1 and RARB genes are common targets for aberrant methylation in cervical cancer." (PMID 25826459, 2015). "We confirmed that DAPK1, RARB, SLIT2, and WIF1 are aberrantly methylated in cervical cancer compared to normal tissue, whereas, APC, CDH1 and FHIT are less commonly methylated." (PMID 25826459, 2015). "The high frequencies of hypermethylation in RARB (40% vs. 38%), CADM1 (50% vs. 44%), and DAPK1 (33% vs. 19%) were shared between HPV-positive OPSCC and cervical cancer." (PMID 25065733, 2014). "Therefore, our study aimed to characterize methylation status of four host genes (RARB, CADM1, DAPK1, and PAX1) that have been studied to a great extent in relation to cervical cancer." (PMID 33718129, 2021). "In addition, this study further substantiated the previous studies results of overall high frequency of methylation rate in promoter regions of RARB, CADM1, DAPK1, and PAX1 genes in cervical cancer subjects." (PMID 33718129, 2021). "In the cervical cancer (HELA) cell line, EGCG (25 μM) suppressed DNMT3B activity and expression, leading to promoter hypomethylation and the reactivation of RARβ, CDH1, and DAPK1." (PMID 32878338, 2020). "Other genes reportedly hypermethylated in cervical cancer with little to no methylation in normal or low-grade CINs include DAPK1, RARB, TIMP3, CCNA and FHIT." (PMID 25826459, 2015). "Cervical cancer and normal cervix tissue was used to select the top 5 discriminating loci among 27 loci in 4 genes (CCNA1, CADM1, DAPK1, JAM3), and one locus of JAM3 (region M4) was identified and confirmed with 267 and 224 cervical scrapings from 2 independent colposcopy referral studies." (PMID 26517242, 2015). "Notably, all eight genes that were frequently methylated in the HPV-transfected cell lines and cervical cancer cell lines (i.e. TP73, ESR1, RARβ, DAPK1, MGMT, CADM1, CDH13 and CHFR) overlapped with those found to be methylated in the cervical carcinoma specimens." (PMID 17971771, 2007). "We observed a significant higher frequency of subjects having promoter methylation signals at the four genes, RARB (94.0%), CADM1 (76.5%), DAPK1 (64.1%), and PAX1 (96.5%), in patients with invasive cervical cancer compared to the subjects without cancer." (PMID 33718129, 2021).